MYO1G (myosin IG)
Description:
Unconventional myosin required during immune response for detection of rare antigen-presenting cells by regulating T-cell migration. Unconventional myosins are actin-based motor molecules with ATPase activity and serve in intracellular movements. Acts as a regulator of T-cell migration by generating membrane tension, enforcing cell-intrinsic meandering search, thereby enhancing detection of rare antigens during lymph-node surveillance, enabling pathogen eradication. Also required in B-cells, where it regulates different membrane/cytoskeleton-dependent processes. Involved in Fc-gamma receptor (Fc-gamma-R) phagocytosis. [Minor histocompatibility antigen HA-2]: Constitutes the minor histocompatibility antigen HA-2. More generally, minor histocompatibility antigens (mHags) refer to immunogenic peptide which, when complexed with MHC, can generate an immune response after recognition by specific T-cells. The peptides are derived from polymorphic intracellular proteins, which are cleaved by normal pathways of antigen processing. The binding of these peptides to MHC class I or class II molecules and their expression on the cell surface can stimulate T-cell responses and thereby trigger graft rejection or graft-versus-host disease (GVHD) after hematopoietic stem cell transplantation from HLA-identical sibling donor. GVHD is a frequent complication after bone marrow transplantation (BMT), due to mismatch of minor histocompatibility antigen in HLA-matched sibling marrow transplants. HA-2 is restricted to MHC class I HLA-A*0201.
Synonyms: HA2; HA-2; HLA-HA2; MHAG
Tractability: Antibody: UniProt places it where antibodies can reach, with high confidence; its Gene Ontology location is reachable by antibodies, with high confidence; the Human Protein Atlas places it where antibodies can reach. PROTAC: ubiquitination databases record sites on it; its protein half-life has been measured.
Gene: Protein-coding gene on chromosome 7 (44,962,662 to 44,979,813, reverse strand). Ensembl gene ENSG00000136286.
Subcellular location: Cell membrane; Cell projection, phagocytic cup
Subcellular location (Human Protein Atlas): Plasma membrane; Nucleoplasm
Gene Ontology:
Molecular function: actin filament binding; phosphatidylinositol-3,4,5-trisphosphate binding; phosphatidylinositol-3,4-bisphosphate binding; phosphatidylinositol-4,5-bisphosphate binding; ATP binding; cytoskeletal motor activity
Biological process: actin filament-based movement; endocytosis; Fc-gamma receptor signaling pathway involved in phagocytosis; T cell mediated immunity; T cell migration
Cellular component: extracellular exosome; membrane; plasma membrane; actin cytoskeleton; microvillus; phagocytic cup; filopodium; lamellipodium; leading edge membrane; myosin complex
Genetic constraint (gnomAD): Loss-of-function variants: 65 observed, 110.32 expected, observed/expected ratio (o/e) 0.59, 90% interval 0.48 to 0.72. The upper end of that interval is the gene's LOEUF score, 0.72, which puts it in group 2 of 6, group 1 being the genes least tolerant of losing a copy. Missense variants: 1,188 observed, 1,317.5 expected, observed/expected ratio (o/e) 0.9, 90% interval 0.86 to 0.95. Synonymous variants: 502 observed, 522.82 expected, observed/expected ratio (o/e) 0.96, 90% interval 0.89 to 1.03.
Homologues: Orthologues: chimpanzee MYO1G (99% identical), guinea pig MYO1G (92% identical), mouse Myo1g (91% identical), rat Myo1g (91% identical), dog MYO1G (90% identical), macaque MYO1G (90% identical), pig MYO1G (86% identical), zebrafish myo1g (61% identical), Drosophila melanogaster Myo31DF (48% identical), Caenorhabditis elegans hum-5 (46% identical). Paralogues in human: MYO1D (60% identical), MYO1C (40% identical), MYO1A (39% identical), MYO1H (38% identical), MYO1B (38% identical), MYO7A (31% identical), MYO7B (30% identical), MYO15A (30% identical), MYO1F (30% identical), MYH7B (30% identical), MYO10 (30% identical), MYO1E (30% identical), and 32 more.